MET (MET proto-oncogene, receptor tyrosine kinase)
Diseases named in the same sentence as MET in open-access papers (continued):
Sharing a sentence is not in itself a finding about the gene and the disease.
medulloblastoma (22 papers, 2008 to 2026). A malignant, invasive embryonal neoplasm arising from the cerebellum. "MET inhibitor crizotinib is currently being assessed for its anti-tumor activity in a pediatric clinical trial, including medulloblastoma (NCT00939770)." (PMID 26496080, 2015). "High expression levels of MET and ErbB2 are correlated with poor clinical outcome in medulloblastoma patients." (PMID 26496080, 2015). "The anti-proliferative effects of crizotinib in our study underscores previous reports analyzing the anti-proliferative effects of MET TK inhibitors in medulloblastoma cell lines and mouse xenograft models." (PMID 26496080, 2015). "This was underscored by the finding that targeting MET using shRNA, results in decreased cell viability in medulloblastoma cell lines." (PMID 26496080, 2015). "More interestingly, high expression levels of both MET and ErbB2 in primary medulloblastoma tissue are correlated with poor clinical outcome in patients." (PMID 26496080, 2015). "Anticipating on these results by the development of novel (pre-) clinical trials with specific TK inhibitors in combination with a MET inhibitor seems very important to improve the clinical efficacy of novel targeted therapies in medulloblastoma in the future." (PMID 26496080, 2015). "Knockdown of MET resulted in decreased cell viability, suggesting that MET is critical in the growth and survival of medulloblastoma cells." (PMID 26496080, 2015). "Hepatocyte growth factor (HGF) and its receptor c-MET are commonly expressed in malignant gliomas and embryonic neuroectodermal tumors including medulloblastoma and appear to play an important role in the growth and dissemination of these malignancies." (PMID 18992144, 2008). "Similarly, MET is a marker of metastasis in SHH medulloblastoma, and it’s inhibition has been shown to decrease proliferation and induce tumor cell apoptosis." (PMID 34667228, 2021). "MET was expressed on the cell surface of our medulloblastoma cell lines." (PMID 26496080, 2015). "The present study investigated the role of micro-environmental growth factors expressed in the brain, such as HGF and EGF, in relation to the effects of hepatocyte growth factor receptor (MET) and epidermal growth factor receptor family (ErbB1-4) inhibition in medulloblastoma cell lines." (PMID 26496080, 2015). "Therefore, MET and all ErbB family receptors might be interesting targets for the treatment of medulloblastoma patients with RTK inhibitors." (PMID 26496080, 2015). "Pharmacological inhibition of c-MET signalling showed that tivantinib outperforms other c-MET inhibitors, including crizotinib and foretinib, in killing SHH medulloblastoma cells." (PMID 41729336, 2026). "Our study confirms that c-MET and its ligand HGF are highly expressed in the SHH medulloblastoma subgroup, with SHH-α and SHH-β subtypes showing the highest expression levels of both genes, respectively." (PMID 41729336, 2026). "Overall, inhibition PDGFA, CXCR4, BOC, MET, and NGFR have all shown therapeutic promise in SHH-subgroup medulloblastoma." (PMID 34667228, 2021). "MET and EGFR were highly activated in primary medulloblastoma samples and subsequently high percentages of medulloblastoma cells expressed these RTK’s." (PMID 26496080, 2015). "Previously with kinome profiling, we observed MET and EGFR/ErbB2 peptide activity in primary medulloblastoma samples." (PMID 26496080, 2015). "Therefore, we started to screen the expression of VEGFR1-3, PDGFRα/β, MET, FGFR1-2 and ErbB1-4 on the cell surface of 5 medulloblastoma cell lines." (PMID 26496080, 2015). "Therefore, MET and ErbB family receptors are interesting targets for RTK inhibitors in the treatment of medulloblastoma patients." (PMID 26496080, 2015).
medulloblastoma (continued). "Flow cytometry analysis revealed that MET (mean±sd: 74.9% ± 13.9%), EGFR (mean±sd: 77.4% ± 10.9%) and ErbB2 (mean±sd: 67.8% ± 10.3%) are highly expressed in all medulloblastoma cell lines, whereas ErbB3 (mean±sd: 4.0% ± 3.6%) and ErbB4 (mean±sd: 1.5% ± 2.1%) are barely expressed at all." (PMID 26496080, 2015). "The combined targeting against MET and FAK could be advantageous for medulloblastoma therapy, and the interaction of FAK with MET was required for HGF-induced cell invasion, whereas Src-dependent phosphorylation of MET requires cell-matrix adhesion, as well as actin stress fiber assembly." (PMID 36430388, 2022). "Various receptor tyrosine kinases (RTK’s) are expressed in medulloblastoma, including vascular endothelial growth factor receptor-2 (VEGFR-2), platelet-derived growth factor receptor α (PDGFRα), hepatocyte growth factor receptor (MET) and epidermal growth factor receptor 2 (ErbB2)." (PMID 26496080, 2015).
pancreatic ductal adenocarcinoma (21 papers, 2014 to 2024). An infiltrating adenocarcinoma that arises from the epithelial cells of the pancreas. "miR-1-3p, miR-23b-3p, miR-34a-5p and miR-130a-3p all have conserved binding sites to MET and can influence the progression of pancreatic ductal adenocarcinoma (PDAC) by targeting MET through the PI3K/AKT signaling pathway." (PMID 36502446, 2022). "After comprehensive analysis, we found that both MET and RIPK2 are related to the prognosis of pancreatic ductal adenocarcinoma and provided some associated clues for clinical application and basic experiment research." (PMID 33204717, 2020). "Presence of this positive FOXM1 and MET feedback loop accelerate pancreatic ductal adenocarcinoma (PDA) development." (PMID 33680951, 2020). "In contrast, a previous study revealed that MUC20 knockdown decreased MET phosphorylation in pancreatic ductal adenocarcinoma cells, suggesting that MUC20 might exert opposite effects on MET phosphorylation depending on the cancer type." (PMID 38439082, 2024). "Previous literature revealed that the upregulation of TGFB2 expression can mediate epithelial-mesenchymal transition of pancreatic ductal adenocarcinoma, and MET, IRS1, and BCL2L1 are also demonstrated to be related to PAAD initiation, progression, and metastasis." (PMID 34777634, 2021). "In addition, the HGF-MET axis regulates mTOR activity and controls serum starvation-mediated autophagy and biogenesis In pancreatic ductal adenocarcinoma, several studies have reported that MET promotes malignant phenotypes and contributes to tumor growth." (PMID 34956177, 2021). "Elevated exo-circPDE8A derived from pancreatic ductal adenocarcinoma (PDAC), promotes lymphatic invasion via stimulating MET by miR-338/MACC1/MET pathway." (PMID 39484707, 2024). "In pancreatic ductal adenocarcinoma (PDAC) tumor tissue, a similar relationship was found between the expression of DYRK1A and c-MET, the hepatocyte growth factor receptor." (PMID 32751160, 2020). "Besides, we predicted that both MET and RIPK2 promote autophagy in pancreatic ductal adenocarcinoma by gene set enrichment analysis." (PMID 33204717, 2020). "Furthermore, HGF-c-MET signaling also leads to activation of the PI3K/AKT pathway and AKT1 has been identified as a direct target of hsa-miR-637 in pancreatic ductal adenocarcinoma cells." (PMID 31063487, 2019).
esophageal cancer (20 papers, 2014 to 2025). A primary or metastatic malignant neoplasm involving the esophagus. "Considering that ESCC is the predominant subtype of oesophageal cancer in China (accounting for approximately 90%), we performed a meta-analysis to assess the prognostic and clinicopathological significance of c-MET protein expression in ESCC." (PMID 40078386, 2025). "In oral and esophageal cancer, it reduces cancer cell growth through suppressing MET signaling by regulating geranylgeranyl diphosphate synthase 1 expression." (PMID 38319449, 2024). "Increased percent c-MET phosphorylation at either Y1234/1235 or Y1356 was observed in one out of two patients with detectable phospho-signal in this study (patient 30, esophageal carcinoma)." (PMID 34180036, 2021). "Finally, it is important to highlight that all clinical trials with MET inhibitors on esophageal cancer included mostly adenocarcinoma cases, making ESCC an unexplored field." (PMID 34037097, 2021). "The results of the analysis showed that c-MET mRNA expression was higher in tumour tissues than in adjacent non-cancerous tissues in most cases, particularly in oesophageal cancer, and this difference was statistically significant (p < 0.001)." (PMID 40078386, 2025). "Copy number abnormalities of MET, CDK6 and EGFR were also observed in esophageal cancer tissues." (PMID 34944989, 2021). "In addition, this finding was validated by the GEPIA database, which integrated datasets from TCGA and GTEx and included more oesophageal cancer samples, further confirming differences in c-MET mRNA expression between tumours and adjacent non-cancerous tissues (p < 0.05)." (PMID 40078386, 2025).
esophageal squamous cell carcinoma (19 papers, 2013 to 2026). Esophageal squamous cell carcinoma (ESCC) is a type of esophageal carcinoma (EC) that can affect any part of the esophagus, but is usually located in the upper or middle third. "ISG15, via the c-MET/Fyn/beta-catenin pathway in esophageal squamous cell carcinoma, shows tumor-promoting effects." (PMID 33123466, 2020). "miR-27a inhibited A549 cell proliferation via MET signaling and in esophageal squamous cell carcinoma functioned as a tumor suppressor through binding to oncogene KRAS." (PMID 32039029, 2019). "Additionally, a study found that miR-1 can impede the growth of esophageal squamous cell carcinoma by downregulating the expression of MET, CDK4, and cyclin D1." (PMID 38504949, 2024). "circLPAR3 is highly expressed in esophageal squamous cell carcinoma (ESCC) tissues and cells, which can upregulate the expression of c-MET through sponge adsorption of miR-198 to increase the migration and invasion of ESCC." (PMID 33937077, 2021). "For example, studies have shown that microRNA LPAR3 can upregulate MET gene expression and activate the PI3K/Akt pathway, promoting the migration, invasion and metastasis of esophageal squamous cell carcinoma (ESCC) cells in vivo and in vitro." (PMID 36502446, 2022).
leukemia (19 papers, 2012 to 2025). A malignant (clonal) hematologic disorder, involving hematopoietic stem cells and characterized by the presence of primitive or atypical myeloid or lymphoid cells in the bone marrow and the blood. "Common mutations found in leukemia patients, such as ABL1, FGFR1, KRAS, MET, NOTCH1, and PTPN11, were also found among our patient population, although not universally." (PMID 37092520, 2023). "Point mutations in kinase domains of RTKs such as EGFR, HER2, MET, KIT, and FLT3 (among others) have been implicated as driver mutations in various cancers such as lung, breast, renal, liver, intestinal, and leukemia." (PMID 22347506, 2012). "Interestingly, we have identified the IL-15 production pathway to be activated in leukemia cells cultured in the 3D BM niche-like AML model, with different associated genes upregulated, including EGFR, IGF1R, MET, RELB, and ERBB2." (PMID 37932837, 2023). "Therefore, targeting c-MET could represent a promising therapeutic strategy for leukemia." (PMID 40520181, 2025). "Cumulative studies also disclosed high expression of c-MET and HGF in different types of lymphoma and leukemia and their microenvironment, respectively; or both in the tumor cells." (PMID 34539876, 2021).
lymphoma (18 papers, 1999 to 2025). A malignant (clonal) proliferation of B- lymphocytes or T- lymphocytes which involves the lymph nodes, bone marrow and/or extranodal sites. "We engineered Ramos Burkitt’s lymphoma cell lines expressing the CT or HLH* EIF3A using the shRNA method as in HEK293T cells and observed a substantial decrease in MYC and MET protein levels in the lymphoma cells expressing the HLH* EIF3A." (PMID 37768948, 2023). "In this review, we will discuss the role of HGF/c-MET pathway in the pathogenesis of lymphoma cells and potential therapies for different types of lymphoma, based on recent published data." (PMID 27923392, 2016). "There are only limited data studying the role of HGF/c-MET signaling pathway in lymphomas, when compared to those from other solid tumors." (PMID 27923392, 2016). "One of the explanation is that c-MET-positive lymphoma cells have retained the physiological growth control by c-MET and possessed high proliferative index, Ki67, resulting in cell cycle progression and possibly chemotherapy sensitivity." (PMID 27923392, 2016). "In the current review, we summarize recent findings about the expression, cellular mechanisms/functions, and therapeutic application of HGF/c-MET in different types of lymphoma, especially B cell lymphoma, T and NK cell lymphoma, and Hodgkin lymphoma." (PMID 27923392, 2016). "We also discuss the existing problems and future directions about studying the HGF/c-MET pathway in lymphoma cells." (PMID 27923392, 2016). "In contrast to other solid tumors, there are limited data describing the functional role of HGF/c-MET signaling pathway in lymphoma." (PMID 27923392, 2016). "We should accelerate clinical trial process by choosing those promising c-MET inhibitors which have been shown to be dramatically effective in lymphoma animal models." (PMID 27923392, 2016). "However, few studies about the role of HGF/c-MET signaling pathway in lymphoma, a group of lymphocyte-derived cancers, have been documented." (PMID 27923392, 2016). "In addition, the expression of c-MET was found in PBMCs from adult T cell leukemia/lymphoma (ATLL) patients and HTLV-1-infected T cell lines." (PMID 27923392, 2016). "We assessed the effect of human HGF/SF on the dissemination of the B-lymphoma cells and found that administration of 5 μg HGF/SF to mice, injected (i.v.)with c-MET-positive lymphoma cells, significantly (P = 0.018) increased the number of metastases in lung, liver and lymph nodes." (PMID 10487611, 1999). "Therefore, future work highlighting more potential mechanisms of activating HGF/c-MET signaling from lymphoma cells may uncover innovative therapeutic strategies for these malignancies." (PMID 27923392, 2016). "It should be highlighted that MET, KDR (VEGFR) STK11 and BRAF are all upstream signaling components in the MAPK pathway and aberrant MAPK signaling is a known oncogenic mechanism in lymphoma." (PMID 29854308, 2018). "HGF influenced the metastasis of c-MET-positive cells into multiple organs, including the liver, kidney, lymph nodes, lung, gonads, and the central nervous system, in SCID mice but did not affect metastasis of c-MET-negative lymphoma." (PMID 27923392, 2016). "However, currently, there are no HGF inhibitors that have been tried in lymphoma treatment, so here, we will focus on c-MET inhibitors, their application in lymphoma treatment." (PMID 27923392, 2016). "So far MET gene CN has not been investigated in malignant lymphoma yet." (PMID 23379953, 2013). "In addition, HGF/SF did not significantly influence dissemination of c-MET-negative lymphoma cells (P = 0.350 with Daudi cells and P = 0.353 with Ramos cells)." (PMID 10487611, 1999).
oral squamous cell carcinoma (18 papers, 2017 to 2025). "MET positivity is independently associated with survival in oral squamous cell carcinoma (OSCC)." (PMID 33996551, 2021). "Use of C- and N-terminal MET monoclonal antibodies (moAbs) has illustrated that MET-EC- occurs in transmembranous C-terminal MET-positive oral squamous cell carcinoma (OSCC)." (PMID 35326642, 2022). "Quantitative scoring of immunohistochemistry showed that the percentage of MET positive cells are significantly increased in oral squamous cell carcinoma (HPV−) compared to oral dysplasia and normal tissue." (PMID 33596979, 2021). "miR-152-3p, through direct targeting of c-MET, suppresses oral squamous cell carcinoma 34, and our results also demonstrated that miR-152-3p inhibitor reduced the c-MET gene transcription and protein expression." (PMID 32194780, 2020). "EGFR (AG1478 and cetuximab) and MET (SU11274) inhibitors also induced changes in actin cytoskeleton organization of oral squamous cell carcinoma cells." (PMID 31649529, 2019). "In immunohistochemistry of an oral squamous cell carcinoma, MET was highly expressed in oral squamous cell carcinoma/HNSCC cases, but not in oral dysplasia and normal tissue." (PMID 33596979, 2021).
clear cell renal cell carcinoma (17 papers, 2015 to 2025). "The main target molecules of cabozantinib, which was used to treat CDC in this case, are c-MET and AXL, which are strongly implicated in the pathogenesis of clear cell renal carcinoma." (PMID 40921965, 2025). "Other variants (BRCA2 (c.5900A>G; p.(Lys1967Arg)), ATM (c.1810C>T; p.(Pro604Ser)) and MET (c.2962C>T; p.(Arg988Cys)) were found in non-syndromic patients (3/74; 4%) with clear cell renal cancer before 50 years of age." (PMID 38002934, 2023). "Further studies showed that the increase in MET copy numbers correlates with poorer survival and distant metastases in clear cell renal cell carcinoma." (PMID 30909397, 2019). "We also found that CAFs interact uniquely with VM cells and tumor cells via HGF/MET and CSPG4 signaling pathways in clear cell renal carcinoma, and its effect on VM cells is significantly higher." (PMID 38694917, 2024). "Cabozantinib, an oral inhibitor targeting MET, AXL, and VEGF receptors, has become a key component of a sequential treatment strategy for clear cell renal cell carcinoma (ccRCC)." (PMID 38398014, 2024).